RNU6-327P (RNA, U6 small nuclear 327, pseudogene)
Gene: Small nuclear RNA gene on chromosome 12 (132,835,374 to 132,835,500, reverse strand). Ensembl gene ENSG00000252079.
Homologues: Orthologues: chimpanzee U6 (98% identical), pig U6 (67% identical), mouse Gm25081 (63% identical). Paralogues in human: RNU6-1011P (67% identical), RNU6-737P (67% identical), RNU6-24P (66% identical), RNU6-354P (66% identical), RNU6-45P (66% identical), RNU6-610P (66% identical), RNU6-86P (66% identical), RNU6-12P (65% identical), RNU6-13P (65% identical), RNU6-26P (65% identical), RNU6-31P (65% identical), RNU6-32P (65% identical), and 1286 more.